CCL13 (C-C motif chemokine ligand 13)
Diseases named in the same sentence as CCL13 in open-access papers (continued):
Sharing a sentence is not in itself a finding about the gene and the disease.
cancer (26 papers, 2015 to 2025). A tumor composed of atypical neoplastic, often pleomorphic cells that invade other tissues. "In addition to CCL2, three other MCP chemokines exist—CCL7 (MCP-3), CCL8 (MCP-2), and CCL13 (MCP-4)—and are implicated in cancer progression." (PMID 39409924, 2024). "Using single cell RNA-sequencing, we observed expression of CCL8, CXCL5, CCL13 and CCL7 in cancer-associated fibroblasts (CAFs)." (PMID 39249543, 2024). "The results showed that both CCL13 and IL10 expression are significantly associated with the infiltrating immunosuppressive cells in all four cancers, including KIRC." (PMID 35692780, 2022). "The discussed group of CC chemokines (CCL2, CCL7, CCL8, and CCL13) have numerous pro-cancer functions, which outweigh their anti-cancer properties." (PMID 33182504, 2020). "After 2 days of co-culture, monocytes exposed to cancer cell lines showed markedly upregulated expression of M1-associated (TNF-α, IL-1β), M2-associated (CCL13, CD206), Mreg-associated (IL-10, TGF-β), and angiogenesis associated (MMP9, VEGF) genes." (PMID 29668679, 2018). "Similar to cancer cell lines, but less dramatically, mf altered the mRNA expression of IL-1β, CCL13, TGM2 and MMP9." (PMID 29668679, 2018). "In particular, CCL13's role in cancer is comparatively well known." (PMID 40692603, 2025). "Due to the recruitment of monocytes, CCL2, CCL7, CCL8, and CCL13 are important in the pathogenesis of many diseases where an important role is played by monocytes and macrophages, in particular atherosclerosis, inflammatory bowel disease, and cancer." (PMID 33182504, 2020). "In the VPP cancers, significant increases were observed in CXCL1, CXCL2, GZMB, IL6, CCL13, and CCL19, among others." (PMID 40361362, 2025). "The analysis demonstrated that expression of four of six proteins (CCL13, IL‐6, CXCL17, and DCN) also differed between the benign lesions and cancer." (PMID 30451357, 2019). "As a seven-transmembrane G protein-coupled receptor, CCR5 can bind to a variety of ligands CCL3 (MIP1α), CCL3L1, CCL4 (MP-1β), CCL5 (RANTES), CCL8 (MCP2), CCL11 (Eotaxin), CCL13 (MCP-4), and CCL16, which are reported to be highly expressed in most malignant tumors." (PMID 36167571, 2022). "There are no studies showing the importance of CCL13 in cancer." (PMID 33182504, 2020). "Additionally, our analysis of chemokines revealed a strong positive correlation between EXO1 expression and CCL7, CCL13, and CCL18 in BRCA, OV, THCA, and UCEC, while a negative correlation was observed with CCL14 and CCL16 in most female-related cancers." (PMID 40433389, 2025).
infection (20 papers, 2007 to 2025). The state of being infected such as from the introduction of a foreign agent such as serum, vaccine, antigenic substance or organism. "In conclusion, these data provide important mechanistic information regarding the nutritional role of vitamin A in infection and inflammation suggested from the co-induction of the M2a markers CCL13 and CCL26 along with the M2c marker IL-10." (PMID 32431691, 2020). "IL-18 was lower on day 2 than at baseline in asthmatics and significantly lower in asthmatic compared to normal subjects on day 4 and IL-4 and CCL13/MCP-4 were also decreased after infection in asthmatics on days 5 and 7 and day 2 respectively." (PMID 28373098, 2017). "Together, these data suggest that baseline myeloid and lymphocyte chemoattractant CCL13 and CCL22 levels in the nose, primarily produced by DCs, may be associated with prevention of infection." (PMID 41354730, 2025). "Nevertheless, these findings suggest that sustained boosting of CCL13 specifically at the site of infection, perhaps by mucosal vaccination or other local immune-stimulating interventions, may be beneficial." (PMID 41354730, 2025). "The up-regulation of some pro-inflammatory cytokines was observed, such as substantial increases of chemokines (CCL13, CCL13 and etc.)compared to their levels prior to infection, and this result suggesting that there is a potentially excessive immune response in the EV71 infection process." (PMID 24392094, 2014). "The E. multilocularis antigen (EmAg) inducible cellular productions of MCP1(CCL13), TARC(CCL17) and PARC(CCL18) were lowest in patients with cured AE and infection-free controls, while the EmAg inducible cellular production of IFN-γ increased after cure." (PMID 35108275, 2022). "The expression of CCL13, CCL19 and CXCL1 was significantly higher in cells infected with the Mtb:Δ-sigH mutant relative to Mtb or Mtb:Δ-sigH:CO at 24 hrs post-infection." (PMID 22235255, 2012). "Additionally, five genes (CCL26, MIR8485, ULBP1, CCL13, CISH) and one unannotated gene (ENSG00000289505) were downregulated in the transwell relative to the other infection groups." (PMID 40630957, 2025).
bacterial infections (1 paper, 2023). "On the other hand, secondary bacterial infections in cirrhotic individuals may be linked to the increase of CCL13 transcript levels in their serum and duodenal mucosa." (PMID 37153575, 2023).
CCL13 also shares sentences with these, for which no sentence is quoted: cyst (7 papers); diabetes (3); gastric cancer (3); Sepsis (3); alopecia areata (2); endometriosis (2); epilepsy (2); Hepatic fibrosis (2); nephritis (2); Neurodevelopmental delay (2); Oral Squamous Cell Carcinoma (2); osteoporosis (2); pseudoexfoliation glaucoma (2); Stroke (2); synovitis (2); acute GVHD (1); aging (1); allergic respiratory disease (1); amaurosis fugax (1); angina pectoris (1); autoimmune disease (1); bacterial meningitis (1); carcinoma in situ (1); chronic obstructive pulmonary disease (1); chronic periodontitis (1); colitis (1); concussion (1); coronary artery disease (1); coronary artery stenosis (1); coronary atherosclerosis (1).
A further 49 diseases each share a sentence with CCL13 in 1 paper.